LUM (lumican)
Diseases named in the same sentence as LUM in open-access papers (continued):
Sharing a sentence is not in itself a finding about the gene and the disease.
tumor (continued). "Some studies have also suggested that lumican plays a key biological role in regulating tumor development and dissemination by using a plethora of signaling cascades to regulate intracellular and extracellular signal transduction." (PMID 32500021, 2020). "Lumican is another small leucine-rich proteoglycan that regulates collagen fibrillogenesis, embryonic development, wound healing, and tumor progression." (PMID 33020183, 2020). "Early reports indicate that lumican is mostly expressed by BC stroma cells and was positively correlated with higher tumor grade, lower expression of ERs, as well as to the younger age of patients." (PMID 32847060, 2020). "Unexpectedly, the inhibition of HDAC11 led to significantly increased LuM, especially when normalizing to the reduced AxLN tumor sizes." (PMID 31519896, 2019). "In general, lumican seems to be a potent agent for the inhibition of tumor progression, which is interesting given that MMP-2 and MMP-9 expression has been reported as positively altered in ALL cases." (PMID 31437251, 2019). "Although the impact of LUM expression on cancer progression seems to be tumor specific, its expression is strikingly upregulated in various tumor sites including lungs, stomach, colon, pancreas, and urinary bladder." (PMID 31861249, 2019). "Studies have demonstrated differential distribution of lumican between cancer cells and the reactive tumor stroma." (PMID 31406961, 2019). "On the other hand, a recent study has demonstrated that glycosylated lumican possesses anti-tumor activity by directly interacting with the catalytic domain of M M P-14 and inhibiting its activity." (PMID 31406961, 2019). "Although quisinostat treatment significantly inhibited AxLN tumor growth, based on luciferase imaging and caliper measurements, quisinostat treatment significantly increased LuM." (PMID 31519896, 2019). "Lumican is a proteoglycan that regulates collagen fibrionogenesis, and it has pro-oncogenic or anti-oncogenic properties depending on tumor type." (PMID 31052560, 2019). "The function of the increased expression of LUM in the prognosis of CCA, is unclear since the role of LUM in carcinomas can show differences based on the type of tumor involved." (PMID 31417643, 2019). "Conversely, in the gastric cancer-associated fibroblasts, lumican activated the (β1 integrin-m ediated FAK signaling, thereby enhancing tumor grow th22." (PMID 31406961, 2019). "MT1-MMP has been shown to cleave LUM, abrogating the suppressive activity that it displays towards tumor cell colony formation." (PMID 30700002, 2019). "Lumican is a proteoglycan that is expressed in both the tumour as the stromal compartment, and directly interacts with tumour cells to inhibit tumour growth by inducing tumour cell quiescence." (PMID 29382042, 2018). "Accordingly, IHC analysis revealed that S100A6, lumican, plastin-2 and 14-3-3 zeta/delta were expressed in the cytoplasm of tumor cells while vimentin was found mainly in the cytoplasm of fibroblasts in periductal fibrotic tissue and tumor stroma." (PMID 30440021, 2018). "For approximately half of all tumor samples (50 and 53 for lumican and versican, respectively) such mRNA data were available." (PMID 28481899, 2017). "Particularly, the co-existence of 2 predominant clusters within viable tissue from tumors implanted in Lum−/− mice constitutes the first evidence for increased intra-tumor heterogeneity induced by the lumican-null phenotype." (PMID 28794454, 2017). "Conjointly, lumican impact on tumor response to matrix-targeted therapy was evaluated considering a previously validated peptide, namely TAX2, that targets matricellular thrombospondin-1." (PMID 28794454, 2017). "At the same time, a previously validated anticancer peptide targeting matricellular TSP-120, 22–24 was considered so as to figure out lumican-related modulation of tumor response to ECM-targeted therapeutic strategies." (PMID 28794454, 2017).
tumor (continued). "Overall, our findings based on innovative and multimodal approaches constitute, to our knowledge, the first demonstration for the key role of extracellular lumican in organizing tumor molecular assembly." (PMID 28794454, 2017). "Next, lumican and versican protein expression levels were compared to their mRNA expression levels in corresponding tumor samples." (PMID 28481899, 2017). "Taken together, the results obtained from this model indicate that (i) lumican acts as a potent endogenous inhibitor of tumor growth, while (ii) newly establishing lumican as a key driver of tumor matrix assembly." (PMID 28794454, 2017). "In contrast, little attention has been given so far in studying lumican direct role in tumor matrix organization." (PMID 28794454, 2017). "The results obtained highlighted a 40% decrease in the collagen content of tumors from Lum−/− mice as compared to WT, thus sustaining a role for collagen in lumican-dependent regulation of tumor ECM assembly." (PMID 28794454, 2017). "Based on original image analysis methodologies, the first experimental evidence that lumican effectively plays a major role in tumor ECM organization is provided in the present report." (PMID 28794454, 2017). "Data obtained further indicate that such lumican-related structural changes are likely to sharply modulate tumor stromal reaction as well as response to matrix-targeting therapeutic strategies, as demonstrated considering TAX2 peptide treatment." (PMID 28794454, 2017). "Altogether, the results obtained present lumican as a strong endogenous inhibitor of tumor growth, while identifying for the first time this proteoglycan as a major driver of tumor matrix coherent assembly." (PMID 28794454, 2017). "In contrast, LUM expression in cancer cells correlated with pleural infusion and larger tumour sizes in ADC." (PMID 29088800, 2017). "Lumican is thought to modify the fibrous tissue surrounding a tumor, thereby inducing a tumor-specific ECM." (PMID 28481899, 2017). "In different tumor models lumican over-expression impaired tumor growth due to a reduced vascular density likely associated with Fas-induced EC apoptosis." (PMID 27809279, 2016). "Considering the important impact of MMP-14 in tumor cell migration and malignant progression and the anti-migratory and anti-tumorigenic role of lumican, we focused on the direct interaction between these two macromolecules." (PMID 26930497, 2016). "In their work, Matsuda Y and colleagues observed lumican immunostaining in both cancer cells and stromal tissues surrounding the tumor and found that tumor size and pleural invasion correlated with the expression levels of lumican in cancer cells." (PMID 25961303, 2015). "The high lumican levels characterizing AdC PEs are probably due to its release by the fibroblasts surrounding the tumor." (PMID 25961303, 2015). "SLRPs, including lumican, have important functions in cell migration, cell proliferation, tissue repair and tumor growth, in addition to their ECM functions in tissue hydration and collagen fibrillogenesis." (PMID 26081832, 2015). "A few genes were differentially expressed (FDR < 0.05) also between STPs and LTPs, among which lumican (LUM), a proteoglycan with an established role in the control of tumor progression that was underexpressed in STPs vs LTPs (Log2FC = −3.25)." (PMID 26188123, 2015). "The biological role of lumican in AdC is elusive and only functional studies will elucidate if it affects tumor progression." (PMID 25961303, 2015). "In AdC surgical samples, lumican expression was low in cancer cells, whereas it was strong and diffuse in the stroma surrounding the tumor." (PMID 25961303, 2015). "In support of this, lumican has been shown to inhibit tumor growth and progression in lung cancer and melanoma." (PMID 26579497, 2015).
tumor (continued). "The results showed that the decorin and lumican proteins were expressed both in normal and tumour prostate tissues at the similar levels and localised mainly in tissue stroma but not in the prostate epithelial cells." (PMID 23691363, 2013). "In most tumor types the tumor stroma is abundant in matrix PGs, particularly versican, lumican, and fibromodulin, and this suggests an important role of stromal PGs in controlling tumor progression." (PMID 24392351, 2013). "Both versican and lumican play a role in the formation of tumor-specific ECM that can support cancer cell growth and metastasis." (PMID 22711178, 2013). "Lumican, another small leucine proteoglycan, has also been demonstrated to display dual anti- or pro-tumoural activity depending of tumour types and is highly correlated to decorin in human MIBC (R = 0.9)." (PMID 24142880, 2013). "Very careful interpretation is applied in this case because of high variation of decorin and lumican levels in individual tumours, up to complete absence." (PMID 23691363, 2013). "Apart from its structural function in the control of collagen fibril assembly, SLRPs, particularly lumican and decorin, can regulate tumor cell behavior." (PMID 24098450, 2013). "Both versican and lumican were expressed in the stromal as well as in the epithelial tumor compartment." (PMID 22711178, 2013). "Lumican interacts with and is regulated by several signaling pathways that can influence tumor progression." (PMID 22711178, 2013). "Lumican, a small leucine-rich proteoglycan of the extracellular matrix, presents potent anti-tumor properties." (PMID 24098450, 2013). "As lumican was shown to be involved in the control of angiogenesis and particularly tumor angiogenesis, the ability of MSC and EPC to form tube-like structures was investigated in vitro." (PMID 23236386, 2012). "This hormone elicited marked increases in bone formation and increased numbers of mature osteoblasts, which express high levels of potential anti-tumor factors that include decorin, lumican, and CYR61." (PMID 21188144, 2010). "The Lum gene, coding for the protein Lumican, is the third most expressed gene in our set of tumours." (PMID 20459814, 2010). "We also observed LUM+/HTR2B + tumor cells close to the mesenchymal component in CRC tissues." (PMID 41034989, 2025). "Certain proteoglycans, such as syndecan-1 and glypican-1, promote tumor growth and dissemination by enhancing growth factor signaling and cell migration, whereas others, including decorin and lumican, inhibit tumor progression by modulating immune responses and collagen fibrillogenesis." (PMID 41303704, 2025). "LUM’s interaction with pathways like PI3K-AKT may uncover mechanisms of tumor progression and therapy resistance, emphasizing the ECM’s role in cancer." (PMID 40789825, 2025). "LUM’s anti-tumour activity stems from specific LUM peptides with anti-tumour activity and its ability to act as an MMP inhibitor, interactive properties with α2β1 integrin also inhibit new blood vessel development required for the nutrition of rapidly expanding tumour cell numbers." (PMID 38474072, 2024). "Previous studies have shown that LUM is expressed in various cancer tissues and is either positively or negatively correlated with tumour progression, influencing cell proliferation, motility, apoptosis, autophagy, angiogenesis regulation, inflammation, immunity, and other functions." (PMID 38594611, 2024). "LUM also has cell directive roles in epithelial-to-mesenchymal transition, cellular proliferation, migration, invasion, and adhesion and is a biomarker of medalloblastoma, where its levels correspond with the aggressiveness of such tumours." (PMID 38474072, 2024). "In addition, we used immunohistochemical images from the HPA database to observe the location and expression levels of LUM protein expression in tumor tissues and normal organ tissues." (PMID 37692065, 2023).
tumor (continued). "We then carried out GSEA analysis to investigate potential LUM involvement in tumor pathways." (PMID 37692065, 2023). "Importantly, the overexpression of NCL and NCAM and the downregulation of DCN and LUM in the NB patient-derived exosomes compared to the CTRL samples was confirmed also in primary tumor tissues." (PMID 37947594, 2023). "Therefore, the link between LUM expression and tumor-infiltrating immune cells in the tumor microenvironment was examined." (PMID 38129820, 2023). "One evaluated the delivery of cytokines fused to the collagen-binding protein lumican in multiple tumor-bearing mouse models, showing prolonged local retention, reduced systemic toxicity, and decreased tumor growth of the injected lesion with an abscopal effect." (PMID 38063196, 2023). "Besides, Noor Momin and colleagues reported two fusion proteins of collagen-binding protein lumican with IL-2 and IL-12, which represented impressive anti-tumor efficacy when administrated individually or jointly in multiple mouse models." (PMID 37692860, 2023). "Therefore, we inferred that LUM promotes tumor invasion and migration by targeting the miR200 family and regulating its downstream signaling pathways." (PMID 33493133, 2021). "Lumican has been characterized as both an anticancer molecule and a tumor promoter." (PMID 34572532, 2021). "On the contrary, some proteolgycans, such as decorin and lumican, could act as tumor suppressors by interacting with key proteins and various receptors." (PMID 34571875, 2021). "Moreover, we found that most of the marker sets of monocytes, tumor-associated macrophages (TAM), M2 macrophages, and DC markers were strongly correlated with the LUM expression in COAD." (PMID 33493133, 2021). "However, recent research efforts have shed more light on the characterization of its roles, which seem to depend on the tumor origin and type and disease stage.Therefore, lumican has been proposed as both a therapy target and anticancer agent." (PMID 34572532, 2021). "Lumican may affect tumour progression, and its sulfotyrosine-rich N-terminal region was shown to be cleaved off by specific MMPs associated with cancer cell invasion in one study." (PMID 32576155, 2020). "The parental LLC cells pre-incubated with lumican displayed an early seeding of cancer cells in the bone in mice after I.C injection, suggesting that incubation with lumican increases the tumor bone metastasis capacity of the parental LLC cells." (PMID 31963522, 2020). "Similar to macrophages, CAFs within the tumor microenvironment may enhance fibrocyte differentiation, potentially though secretion of the proteoglycan, lumican." (PMID 32731354, 2020). "During the process of bone remodeling, the ECM components are released into bone microenvironment and create a concentration gradient of ECM proteins, including lumican, which may act as a chemoattractant to induce the migration of tumor cells in bone marrow." (PMID 31963522, 2020). "However, LUM can induce proteoglycan composition changes and regulate the cell cycle to participate in tumour development." (PMID 32319226, 2020). "In addition, LUM expression levels were different in groups classified according to tumor differentiation, pathological stage, and T stage." (PMID 32500021, 2020). "This three-dimensional acellular portion is composed by fibrous proteins (e.g., collagen, fibronectin, laminin, proteoglycans (e.g., decorin, biglycan, and lumican)) and water, and represents a dynamic structure in continuous remodeling, especially during tumor progression." (PMID 32012917, 2020). "Aberrant expression of LUM can further affect the metastasis and invasion of tumour." (PMID 32319226, 2020). "Hence, the results demonstrated in this study indicated that lumican promotes tumor cell adhesion and invasion, as well as the incidence of bone metastasis of tumors, via an autocrine regulatory mechanism." (PMID 31963522, 2020).
tumor (continued). "In addition, the expression level of LUM was different in groups classified according to tumor differentiation (P < 0.001), pathological stage (P < 0.001), and T stage (P < 0.001)." (PMID 32500021, 2020). "Thus, during the adhesion of the tumor cells to a coating of lumican, a reorganization of the cytoskeleton is observed." (PMID 32478070, 2020). "The loss of collagen fibers organization due to the absence of lumican can potentially increase the accessibility of anti-cancer drugs to the tumor." (PMID 32478070, 2020). "The expression of lumican in tumor tissues has been the focus of many studies in recent years." (PMID 32500021, 2020). "LUM has also been identified as an inhibitor for tumor angiogenesis." (PMID 32063855, 2019). "However, in colorectal cancers lumican is up-regulated and tumor cells show increased migration by actin remodeling." (PMID 31052560, 2019). "Thus, LUM is thought to exhibit an antiangiogenic effect in restricted circumstances, possibly only in some specific tumor microenvironments." (PMID 32063855, 2019). "Thus, decorin is a strong tumor suppressor whereas, the expression of lumican needs to be specifically correlated to the tumor type and stage during the disease progression to draw more relevant conclusions." (PMID 29559954, 2018). "Lumican, a class II small leucine-rich proteoglycan, plays major roles in the organization of extracellular matrix (ECM) and is an important modulator of biological functions including tumor-associated inflammation." (PMID 29549325, 2018). "Suppression of lumican also reduces tumor growth and metastasis in experimental animals." (PMID 30440021, 2018). "The lower expression of lumican might be explained by the rapid progression of this tumour, but also by its low percentage of viability." (PMID 28332606, 2017). "In addition, we found a sound overexpression of the extracellular protein lumican in LTPs as compared to ST ones, still corroborating the view of a great involvement of tumor microenvironment in the definition of long-term vs short-term survivors." (PMID 26188123, 2015). "To this end, we investigated the involvement of DCN and LUM in GBM and NB CSC-like models, simulating the phenomena of anchorage loss and the detachment of differentiated tumor cells that underlie the EMT process, and their relationship to CSC-like behavior and the cell response to TMZ." (PMID 26230845, 2015). "In breast and pancreatic cancers, high stromal lumican was associated with advanced cancer stage, invasion, and poor survival, whereas a negative correlation was found between tumor grade and expression in neuroendocrine tumors of the colon." (PMID 26579497, 2015). "However, stage II patients positive for lumican expression in the epithelial cells overall in the tumor did show a trend toward longer DSS (DFS P = 0.2, DSS P = 0.05)." (PMID 22711178, 2013). "Lumican expression was also correlated to several tumor characteristics." (PMID 22711178, 2013). "We compared the performance of the 19-CNI ‘signature’ to a ‘clinical’ model that included patient age at diagnosis, lymph node status, and tumor size and a ‘clinical + subtype’ model that included clinical covariates combined with tumor subtypes (i.e., LUM A, LUM B, TNBC, and HER2+)." (PMID 21858162, 2011). "Our observations appear to be consistent with the very interesting emerging evidence of a broader role of PDGFRs in tumor stromogenesis, and with the increasing interest in the role of decorin and lumican via the tyrosine kinase receptor family in cancer biology." (PMID 20421977, 2010). "Furthermore, ECM components, such as collagen isoforms, Fibrillin-1, EMILIN-1, Prolargin, and Lumican, were found to be highly expressed in the MLH1/PMS2-deficient tumor area, suggesting a connection between DNA repair deficiencies, ECM remodeling, and tumor progression." (PMID 40076915, 2025). "Interestingly, activation of the AKT signaling pathway is observed in the LUM+ tumor cells." (PMID 39685635, 2024).